INS (insulin)
Diseases named in the same sentence as INS in open-access papers (continued):
Sharing a sentence is not in itself a finding about the gene and the disease.
type 1 diabetes (continued). "The purple cluster contained four major keywords: type 1 diabetes, nod, glucose, and insulin." (PMID 36908460, 2023). "Additionally, research in 3D bioprinting has expanded to address the management of diseases like type 1 diabetes by printing human beta-like cells capable of insulin secretion in response to glucose." (PMID 37627795, 2023). "Type 1 diabetes is an immune-mediated disease that results from destruction of the insulin-secreting beta cells in the pancreas, necessitating lifelong treatment with exogenous insulin." (PMID 37743383, 2023). "We hypothesize that increased insulin demand due to upregulated sugar molecules in the circulation is one of the non-exclusive triggers contributing to the rapid manifestation of type 1 diabetes." (PMID 37745723, 2023). "Inferior protection of insulin-producing cells against viruses is even regarded as one of potential triggers for the development of the β-cell targeted autoimmune response and subsequent type 1 diabetes." (PMID 37545890, 2023). "Unlike type 1 diabetes, gestational diabetes is not caused by a lack of insulin but by other hormones produced during pregnancy that can make insulin less effective." (PMID 37149790, 2023). "Insulin pump therapy is becoming increasingly recommended for patients with type 1 diabetes." (PMID 37185052, 2023). "Firstly, we only included adult patients with type 1 diabetes; therefore, the applicability of our findings to type 2 patients on intensive insulin treatment or to pediatric patients is unknown." (PMID 36900956, 2023). "An increased level of sugars in circulation demands higher insulin secretion, leading to beta-cell stress that could contribute to rapid progression to symptomatic type 1 diabetes." (PMID 37745723, 2023). "This full-length INS mRNA has been shown to generate an insulin defective ribosomal product (INS-DRiP), in particular under endoplasmic reticulum (ER) stress, which is a target of islet autoimmunity and associated with type 1 diabetes pathology." (PMID 36884057, 2023). "This could be particularly useful in regenerative medicine and cell replacement therapies by differentiating patient-derived iPSCs to functional cell types such as insulin-producing beta-cells for Type I diabetes patients." (PMID 36697417, 2023). "Interestingly, methyldopa (an analogue of DOPA) can block the activation of insulin-autoreactive T cells in NOD mice and prevented beta cell loss and IAA in recent-onset type 1 diabetes." (PMID 36207582, 2023). "A facility manager added, “Type 1 diabetes and insulin are rarely seen and therefore less relevant, but also where it is needed, sufficient capacity may not exist to facilitate its use, as proper cold chain systems are lacking”." (PMID 37277827, 2023). "During puberty, male children develop more lean body mass whereas female children gain more fat mass, a physiological change which might be amplified in type 1 diabetes by the amount of insulin used." (PMID 36700969, 2023). "Eleven patients reported taking extra medications when infected; Nine with adrenal insufficiency took glucocorticoids, one with type 1 diabetes increased insulin doses, while one had hypertension and also administrated more of the active vitamin D-drug Etalpha." (PMID 37346050, 2023). "Type 1 diabetes (T1D) results from immune-mediated destruction of insulin-producing beta cells." (PMID 37794169, 2023). "One study found that a 25% dose reduction of insulin degludec did not reduce the risk for hypoglycaemia in people with type 1 diabetes during 5 consecutive days of moderate-intensity activity, but this study was very small (n=7)." (PMID 36879098, 2023). "The BEGIN trial was a phase III trial comparing insulin degludec and insulin glargine U100 in people with type 1 diabetes without increased risk of hypoglycemia." (PMID 38089060, 2023).
type 1 diabetes (continued). "While exogenous insulin therapy remains the standard treatment, allogeneic transplantation of either whole pancreas organs or isolated pancreatic islets have emerged as validated therapeutic approaches in patients with severe forms of type 1 diabetes (T1D)." (PMID 38213551, 2023). "Evidence has shown that leptin could substitute for insulin to control blood sugar fluctuations in patients with type 1 diabetes." (PMID 37373070, 2023). "One notable example is the Diabetes Eating Problem Survey—Revised (DEPS-R), a 16-item questionnaire validated in youth with type I diabetes, which includes questions related to insulin manipulation and intentional achievement of hyperglycemia and ketosis for the purposes of weight loss." (PMID 37686703, 2023). "The Kobe Best Basal insulin study has examined treatment differences between insulin degludec and insulin glargine U300 in people with type 1 diabetes without increased risk of severe hypoglycemia." (PMID 38089060, 2023). "It is impossible to avoid insulin for patients with type 1 diabetes." (PMID 37840692, 2023). "However, 1 patient who was receiving Infliximab and had type 1 diabetes, requiring insulin treatment, needed to be hospitalized." (PMID 37382255, 2023). "Consequently, insulin production decreases, and hyperactive alpha cells increase glucagon secretion in Type 1 Diabetes Mellitus (T1DM) patients." (PMID 38149165, 2023). "However, it is suggested that insulin degludec carries the same risk for post-exercise (nocturnal) hypoglycaemia compared with insulin glargine in people with type 1 diabetes." (PMID 36879098, 2023). "Notably, type 1 diabetes is accompanied by disorders in lipid metabolism, including alterations in lipoprotein metabolism where insulin plays a central regulatory role." (PMID 37537394, 2023). "Additionally, insulin injection has been demonstrated to suppress the expression of myostatin in type 1 diabetic rats." (PMID 37576807, 2023). "Our findings support the concept that oxidative stress, and neoantigenic epitopes of insulin, may be involved in the immunopathogenesis of type 1 diabetes." (PMID 36207582, 2023). "The insulin-induced reduction of plasma amino acid concentration and release from endogenous proteolysis could be demonstrated in type 1 diabetes subjects too, also in the post-prandial state." (PMID 38201949, 2023). "However, even in the absence of measurable impairment of the glucose profile, changes in insulin secretion and sensitivity have been described in the early stages of type 1 diabetes." (PMID 37712956, 2023). "It is worth noting that diabetic patients are at risk for poor perioperative glycemic control or pulmonary aspiration and that patients with type 1 diabetes are insulin deficient, not insulin resistant." (PMID 36756379, 2023). "Type 1 diabetes, which is insulin-dependent, is an autoimmune disease caused by the destruction of pancreatic β-cells, which secrete little or no insulin." (PMID 36984794, 2023). "However, it is important to note that the algorithm used in this study has a considerably enhanced adaptivity to allow for more responsive insulin dosing compared with currently available hybrid closed-loop systems for the treatment of type 1 diabetes." (PMID 36449375, 2023). "The main purpose of the screening is to diagnose presymptomatic type 1 diabetes so that affected children and their families can be educated and monitored, and so that patients can begin insulin therapy early enough to prevent serious metabolic derangements at the onset of clinical disease." (PMID 37329450, 2023). "Yet, INS associated protection is not complete and around 20% of type 1 diabetes patients carries a copy of the ‘protective’ INS variant." (PMID 36701305, 2023). "Type 1 diabetes is a medical condition characterized by the body’s inability to produce insulin." (PMID 37724233, 2023). "This means that the external supply of insulin is vital for treatment of type 1 diabetes." (PMID 38074488, 2023).
type 1 diabetes (continued). "In conclusion, our findings support the concept that oxidative stress, and neoantigenic epitopes generated by oxPTM of beta cell antigens such as insulin, may be involved in the pathogenesis of type 1 diabetes." (PMID 36207582, 2023). "The related reasons may be related to the earlier onset of type 1 diabetes, the difficulty of controlling insulin levels, and the heavier clinical manifestations." (PMID 38152330, 2023). "Given the role of insulin as a major autoantigen in type 1 diabetes, the findings from these latter studies are also consistent with altered/reduced presentation of insulin antigens, leading to slower autoimmunity progression and lower type 1 diabetes penetrance in NOD mice." (PMID 37488322, 2023). "Finally, only one participant was treated with insulin, which mainly limited the results of the study to non-insulin-dependent diabetes." (PMID 37267406, 2023). "Another study described the case of a nine-year-old child with type 1 diabetes, in whom, after following a ketogenic diet, insulin administration could have been discontinued." (PMID 36771207, 2023). "Type 1 diabetes: Type 1 diabetes, also referred to as insulin-dependent or juvenile diabetes, is an autoimmune condition characterized by the erroneous targeting and destruction of the insulin-producing beta cells in the pancreas by the body’s immune system." (PMID 37724233, 2023). "Furthermore, insulin use contributes to the preservation of muscle mass in type 1 diabetes patients and is thought to prevent sarcopenia." (PMID 37424302, 2023). "However, morning exercise leads to a lower risk of late-onset hypoglycaemia compared with afternoon exercise in people with type 1 diabetes on insulin pump therapy." (PMID 36879098, 2023). "Type 1 diabetes is a complex, chronic disease in which the insulin-producing beta cells in the pancreas are sufficiently altered or impaired to result in requirement of exogenous insulin for survival." (PMID 37538198, 2023). "Conversely, some participants who used insulin only in 2013 and subsequently had other medications added, may have had type 1 diabetes." (PMID 37874829, 2023). "Glycemic variability remains frequent in patients with type 1 diabetes treated with insulin pumps." (PMID 37973963, 2023). "Patients with type 1 diabetes need to use insulin throughout their life to maintain life, and even regular use of insulin cannot simulate the physiological endogenous insulin secretion pattern, resulting in large fluctuations in blood sugar, enhanced health care costs, and reduced quality of life." (PMID 36761194, 2023). "Type 1 diabetes (T1D) is an autoimmune disease that causes pancreatic β-cell damage, leading to a decrease in insulin synthesis or a complete lack of insulin secretion in patients, which results in elevated blood glucose." (PMID 37957681, 2023). "In addition to adverse effects on insulin sensitivity, elevated plasma BCAAs stimulate insulin secretion, deplete insulin reserves in early type 1 diabetes, impair pancreatic β cell function, and ultimately leads to insulin deficiency." (PMID 36761194, 2023). "Automated Insulin delivery devices(AID) can revolutionize type 1 diabetes management and have evolved to incorporate calibration free/reduced sensors, whose impact on user experience in Medtronic devices is unknown." (PMID 37693343, 2023). "Type 1 Diabetes (T1D) is a multifactorial disease with a strong genetic component that results from the immune-mediated destruction of insulin-producing pancreatic beta cells, leading to lifelong insulin dependency." (PMID 38318503, 2023). "It is unclear whether hybrid closed-loop (HCL) therapy attenuates the metabolic impact of missed or suboptimal meal insulin bolus compared with sensor-augmented pump (SAP) therapy in children with type 1 diabetes in free-living conditions." (PMID 36927054, 2023). "Type 1 diabetes (T1D) results from autoimmune destruction of insulin-producing pancreatic β-cells." (PMID 37256143, 2023).
type 1 diabetes (continued). "In contrast, individuals with type 1 diabetes are unable to regulate their own insulin levels following subcutaneous delivery, and they often exhibit diminished glucagon and epinephrine responses to hypoglycemia, thereby making them much more vulnerable to low blood glucose." (PMID 37166980, 2023). "One patient developed type 1 diabetes presenting with diabetic ketoacidosis after three cycles of treatment with PD-1 inhibitor combined with chemotherapy and required permanent exogenous insulin treatment." (PMID 37359533, 2023). "Similarly, expressing the transcription factors Pdx1 and MafA in neighboring α cells can convert these cells into functional, insulin-producing β cells that appear resistant to autoimmune destruction in models of type 1 diabetes." (PMID 36706177, 2023). "He subsequently developed an insulin dependent diabetes, for which he received insulin." (PMID 35765291, 2022). "Type 1 diabetes is mostly treated with manual insulin injections or insulin pumps." (PMID 35808386, 2022). "Adolescent girls with type 1 diabetes expressed how the insulin pump could make them feel different about their bodies and how they tried to hide it for fear of not being accepted by their peers." (PMID 36315239, 2022). "Managing Type 1 diabetes requires insulin injection to lower blood glucose levels." (PMID 36145160, 2022). "Indeed, Mehra er al. demonstrated that restoring insulin concentrations in young adult type 1 diabetic patients through pancreas transplantation improved nerve density and length, supporting the importance of insulin in preventing peripheral nerve damage." (PMID 36703927, 2022). "The incidence rate of severe hypoglycemia in persons with type 1 diabetes on insulin is 7.1%." (PMID 36687427, 2022). "During the analyzed period, the main drivers of the increasing costs in outpatient care were the introduction of innovative drugs, the reimbursement of self-monitoring of blood glucose in insulin-treated persons, HbA1c, and insulin pumps in those with type 1 diabetes." (PMID 36011670, 2022). "The innovative new initiative from the University of Birmingham may permit people with type 1 diabetes to get rid of routine insulin injections." (PMID 36381916, 2022). "Also, during the years in which the included adolescents in our study were born, very few pregnant women with type 1 diabetes were using an insulin pump, and less than 50% were treated with human insulin." (PMID 35472047, 2022). "In some cases, insulin injections may also be given; however, this is usually administered to individuals with type 1 diabetes." (PMID 35055576, 2022). "Also in IVGTT studies baseline first-phase insulin response (FPIR) values seem to be decreased in children progressing to type 1 diabetes as early as 4–6 years before diagnosis suggesting early β-cell dysfunction." (PMID 36171903, 2022). "Type 1 diabetes, which mostly occurs in adolescents and children, is mainly caused by autoimmune problems, destroying pancreatic β-cells, leading to a lack of insulin and requiring insulin injections." (PMID 35162956, 2022). "Enteroviral infection has been implicated consistently as a key environmental factor correlating with the appearance of autoimmunity and/or the presence of overt type 1 diabetes, in which pancreatic insulin-producing beta cells are destroyed by an autoimmune response." (PMID 35867130, 2022). "It is often the first presentation of type I diabetes and can also occur due to a lack of compliance with insulin therapy or infection, among other causes." (PMID 36505109, 2022). "For patients with type I diabetes mellitus, providing Insulin is crucial; however, type II diabetic patients may administer it in the later stages." (PMID 36381916, 2022).
type 1 diabetes (continued). "With 1-in-4 patients in the United States with type 1 diabetes reporting difficulties affording insulin, there is concern that some of these patients might look for cost savings on the internet, unaware that 96% of internet pharmacies are illegitimate." (PMID 35156937, 2022). "In 33 patients with non-insulin-dependent diabetes, pinitol at 400 mg thrice a day for a tenure of 3 months is reported to exert antidiabetic action by declining the fasting plasma glucose content and enhancing the secretion of insulin." (PMID 36557843, 2022). "However, this is a difficult situation to manage because patients with type 1 diabetes usually need to decrease insulin to prevent hypoglycaemia." (PMID 35577814, 2022). "Indeed, dystrophin cleavage is a well-known mechanism of EV-B pathogenicity inducing dilated cardiomyopathy, whereas insulin production decrease is the first step of type 1 diabetes development." (PMID 36016091, 2022). "A decrease of 8.80 visits in patients with type 1 diabetes might have resulted in the failure to prescribe the necessary insulin, which could have been life-threatening." (PMID 35691909, 2022). "For example, the Dose Adjustment for Normal Eating (DAFNE) study, with a flexible and intensive 5-day single course in the treatment of adults with type 1 diabetes with insulin, provided major long-term benefits for quality of life outcomes and treatment satisfaction." (PMID 36443739, 2022). "For the treatment of diseases such as type I diabetes that requires insulin release regulated by the patient's metabolic needs, microencapsulation may be the most effective therapeutic strategy." (PMID 35674842, 2022). "Moreover, alterations in sleep habits are associated with high levels of Hemoglobin A1c (HbA1c) in young people with type 1 diabetes and with increased insulin requirements." (PMID 36291855, 2022). "Type 1 diabetes (T1D) is an autoimmune condition that destroys insulin-secreting b cells." (PMID 36233287, 2022). "Patients with type 1 diabetes are subject to exogenous insulin injections, whether manually or through (semi)automated insulin pumps." (PMID 35577814, 2022). "As highlighted by the Lancet Diabetes Commission, access to insulin, patient education, and tools for monitoring blood glucose concentration are important to prevent premature deaths and emergencies in young patients with type 1 diabetes." (PMID 35143780, 2022). "The delivery of encapsulated islets or stem cell-derived insulin-producing cells (i.e., bioartificial pancreas devices) may achieve a functional cure for type 1 diabetes, but their efficacy is limited by mass transport constraints." (PMID 36229614, 2022). "Almost 22 million people were living with type 1 diabetes in 2019,12 needing insulin daily." (PMID 35143780, 2022). "Insulin pumps improve glycemic control and quality of life in children with type 1 diabetes (T1D)." (PMID 35507342, 2022). "Nowadays, however, we know that insulin-producing cell loss in type 1 diabetes does not seem to be linear and that remaining beta cell mass is maintained through spontaneous regeneration and stimulated recovery." (PMID 34510360, 2022). "The effect of insulin on BCAA plasma levels has been investigated for the first time in patients with type 1 diabetes and results showed that the withdrawal of insulin treatment was associated with a substantial increase in circulating BCAA concentrations, as confirmed by others." (PMID 35931683, 2022). "All 14 women with type I diabetes continued using insulin beyond the postpartum period." (PMID 35585514, 2022). "However, after many analyses by clinicians, it has been proven that insulin Degludec is superior to insulin glargine in both diabetic diseases (i.e., diabetes type-I and II)." (PMID 35723344, 2022). "Patients with insulin-dependent diabetes or inadequate insulin reserve might have inadequate endogenous insulin secretion." (PMID 36371171, 2022).